RNU6-368P (RNA, U6 small nuclear 368, pseudogene)
Gene: Small nuclear RNA gene on chromosome 9 (67,869,947 to 67,870,053, forward strand). Ensembl gene ENSG00000278551.
Homologues: Orthologues: chimpanzee U6 (99% identical), macaque U6 (93% identical), dog U6 (70% identical), mouse Gm54642 (61% identical), mouse Gm22279 (59% identical), rat LOC120101210 (58% identical). Paralogues in human: RNU6-1193P (100% identical), RNU6-1269P (100% identical), RNU6-538P (100% identical), RNU6-1320P (99% identical), RNU6-599P (99% identical), U6 (97% identical), U6 (96% identical), RNU6-316P (95% identical), RNU6-55P (95% identical), U6 (95% identical), RNU6-954P (94% identical), RNU6-821P (87% identical), and 1288 more.